S100A10 (S100 calcium binding protein A10)
Diseases named in the same sentence as S100A10 in open-access papers (continued):
Sharing a sentence is not in itself a finding about the gene and the disease.
tumor (continued). "The analysis disclosed that S100A10 expression showed a positive correlation with tumor proliferation, G2M checkpoint activity, epithelial-mesenchymal transition (EMT), DNA replication, and DNA repair processes, whereas a negative correlation was found with galactose metabolism." (PMID 39840058, 2024). "Utilizing RNA-seq technology and bioinformatics analysis, our study revealed that S100A10 is highly expressed in tumor tissues, which can predict the survival time of HCC patients and is strongly correlated with the infiltration level of CD8+ T cells in HCC tissues." (PMID 39117605, 2024). "By modulating the Src/annexin A2/AKT/mTOR signaling pathway, S100A10 could promote pro-tumor aerobic glycolysis, suppress cell apoptosis, and maintain cell proliferation." (PMID 37892132, 2023). "Similarly, expression of S100A10 mRNA in tumor tissues was significantly higher than that in para cancer tissues (P < 0.01)." (PMID 37420211, 2023). "Consistently, in vivo xenograft experiments revealed that on day 27, the tumor weights in the sh-NC and sh-S100A10 groups were 302.07 ± 36.91 mg and 120.93 ± 25.00 mg (P < 0.01), respectively, whereas the respective tumor volumes were 435.55 ± 76.63 mm3 and 167.81 ± 37.28 mm3 (P < 0.01)." (PMID 37781076, 2023). "S100A10 is closely tied to the regulator of diverse pathophysiological processes, and in oncogenic settings it can reportedly shape intratumoral angiogenesis, intratumoral circulation, and tumor cell invasivity, migration, and metastatic progression." (PMID 37781076, 2023). "S100A10 (p11) is one of twenty-five different S100 family members of proteins, of which most are genes located on chromosome 1q21, which is amplified in several neoplastic diseases." (PMID 37892132, 2023). "In addition, a higher S100A10 protein expression was also detected in PDAC tissues than that in pancreas non-tumor tissues in the HPA database and human PDAC specimens." (PMID 36612197, 2022). "Furthermore, S100A10 expression is correlated with tumor development, invasion, poor prognosis and further can act as a biomarker due to its expression in various tumor cells." (PMID 36230614, 2022). "TPM3, CHMP4C, EEF1A1, FASN, TNF, S100A10, and IL1A represent a high-risk score and poor prognosis, suggesting that these genes may be associated with the tumor process in patients with CC and appear to be pro-oncogenes." (PMID 36685937, 2022). "In this assessment, we found that the size of orthotopic pancreatic tumors in the shS100A10 group was significantly smaller than those in the shNC control group, and the protein expression levels of S100A10 and Ki-67 were significantly inhibited in the tumor tissues of shS100A10 group." (PMID 36612197, 2022). "Our results have shown that vascular co-opted vessels could be recognized as metabolically overactive (evaluated as mitochondria expression) P-gp+ or S100A10+ tumor cells surrounding CD31+ endothelial cells with reduced P-gp and mitochondria expression." (PMID 36553127, 2022). "In addition, the expression of S100A10 was mainly distributed in the cytoplasm of tumor cells in group I (-d)." (PMID 34336846, 2021). "S100A10 was identified to be an independent predictor of tumor recurrence." (PMID 34944416, 2021). "Similarly, a recent IHC of membranous S100A10 expression in 120 primary squamous cell lung carcinoma tissues from patients in Japan showed intense staining in the invasive front of the tumor tissue which was directly in contact with the stroma." (PMID 34944416, 2021). "In human CRC tissues, the expression level of S100A10 was positively correlated with tumor differentiation, and the positive rate of S100A10 nuclear localization was the highest in the poorly differentiated CRCs compared with that in well and moderately differential CRC." (PMID 34336846, 2021). "The data proved S100A10 expression was positively related to subcutaneous tumor size." (PMID 34178044, 2021).
tumor (continued). "Membranous positivity for S100A10 was diffusely found in both tumor buds and PDCs." (PMID 33160379, 2020). "Furthermore, a part of the luminal surface of tumor glands showed a positivity for S100A10 and ANX A2." (PMID 33160379, 2020). "Congruously, the tumor cells with Ras transformation display a substantial reduction or a loss in the generation of plasmin in the absence of S100A10." (PMID 31949486, 2020). "Therefore, S100A10 is a pivotal regulatory factor for tumor progression, especially for the invasiveness and metastasis of tumor cells." (PMID 31949486, 2020). "In terms of the mechanisms of tumor invasiveness, S100A10, as a plasminogen receptor, might play a cooperative role with Ras." (PMID 31949486, 2020). "Furthermore, the potential mediatory roles of S100A10 in non-tumor diseases were also discussed (Figure." (PMID 31949486, 2020). "The results of the present study clearly demonstrate that S100A10 knockdown resulted in decreased proliferation and colony formation ability, increased apoptosis rate in vitro and inhibited tumor growth in vivo, advancing the current understanding of the involvement of S100A10 in tumorigenesis." (PMID 31739800, 2019). "Therefore, we postulate that K47 succinylation stabilizes S100A10 by inhibiting its ubiquitylation and subsequent proteasomal degradation, which enhances plasminogen activation and promotes tumour cell invasion and migration." (PMID 30394687, 2019). "To further examine whether S100A10 was responsible for tumor growth in vivo, we subcutaneously injected A2780 cells transfected with shGFP, shS100A10–1 or shS100A10–2 into the flanks of NOD/SCID mice." (PMID 31739800, 2019). "We also explored the role of S100A10 in tumor growth in vivo." (PMID 31739800, 2019). "Our results suggest that downregulation of S100A10 suppresses tumor growth in vivo." (PMID 31739800, 2019). "It should be noted that S100A10‐depleted Panc‐1 cells have similar proliferation rates in vitro which suggests that the in vivo effects are likely mediated by the microenvironmental interactions with tumor cells." (PMID 30009399, 2018). "It remains unclear whether the reduced tumor growth is due to the plasminogen‐dependent function of S100A10 or a novel intracellular function related to apoptosis or proliferation." (PMID 30009399, 2018). "S100A10 was shown to mediate the migration of macrophages to the tumor site." (PMID 29379499, 2017). "Intraperitoneal injection of wild-type macrophages restored macrophage density within the tumor, but injection of S100A10-deficient macrophages did not." (PMID 29379499, 2017). "Thus, our present study provides basic findings to support that S100A10 expression can be used as a predictive marker for tumor sensitivity to L-OHP." (PMID 24851084, 2014). "S100A10 is also a potential inducer of nuclear factor-κB (NF-κB) via activation of the Akt pathway, which is involved in cell growth, anti-apoptotic signaling, and carcinogenesis in tumor cells." (PMID 24851084, 2014). "Also included are proteins previously implicated in tumor progression in other cancer types (e.g., CTGF, TIMP1, S100A10) and proteins that we have identified in proteomics screens of other tumor models (unpublished data)." (PMID 24618895, 2014). "S100A10 acts as a key molecule for the promotion of angiogenesis and tumor metastasis, and annexin A2 is believed to act as a scaffolding protein to secure S100A10 to the cell surface, considering the well-established roles of S100A10 in cellular plasmin regulation." (PMID 24851084, 2014). "Moreover, S100A10 expression correlated with tumor recurrence in stage II and III colon cancer patients treated with 5-fluoruracil." (PMID 23519104, 2013). "Further genetic studies have shown that S100A10 plays a crucial role in the recruitment of macrophages to the tumor site, which may be mediated by S100A10-stimulated plasmin generation." (PMID 23598417, 2013).
tumor (continued). "In addition, S100A10 and Annexin A2 form isodimers, prompting the invasion and metastasis of the tumor by activating plasminogen." (PMID 19638242, 2009). "Furthermore, the plasminogen activation system operates through specific cell surface receptors like annexin A2/S100A10 complexes that can be delivered to distant organs via tumor-derived exosomes (or activated locally in the resident fibroblasts and immune cells)." (PMID 41463352, 2025). "Finally, we investigated whether PDAC tumor growth was linked to the primary substrate of plasmin proteolytic activity and the expression of plasminogen receptors, including Plg‐RKT and S100A10 by tumor cells." (PMID 37971174, 2024). "Moreover reduction of S100A10 in PANC‐1 reduced orthotopic tumor growth in mice." (PMID 37971174, 2024). "The plasminogen receptors ENO1, histone H2B, Plg-RKT, ANXA2 and S100A10 have been shown to be expressed at the cell surface of human monocytes/macrophages, where they are involved in plasminogen activation and play an important role in the recruitment and migration of macrophages to tumour sites." (PMID 35204653, 2022). "Moreover, rapamycin treatment further inhibited the promoting effect of S100A10 on tumor growth." (PMID 33324631, 2020). "Interestingly, intratumoral injection of macrophages of either genotype could rescue tumor growth, suggesting that S100A10−/− macrophages still have the ability to stimulate tumor growth but lack the ability to invade into the tumor." (PMID 29379499, 2017). "In contrast, S100A10, a carboxyl-terminal lysine-containing plasminogen receptor has been shown to account for the generation of as much as 90% of the cell surface plasmin generation and has been shown to play an important role in both tumor growth and metastasis." (PMID 27351226, 2016). "Whether or not loss of S100A10 in the tumour microenvironment exerts a functional role in follicular thyroid neoplasia is a subject of future investigations." (PMID 25880590, 2015). "In DEN-treated mice, S100A10 and S100A11 were downregulated at 7 months (before tumor formation) up to 11 months of age (time of sacrifice)." (PMID 40841353, 2025). "Key plasminogen receptors, including annexin A2, S100A10, alpha-enolase (ENO1), are detected in tumor-derived vesicles, and histone H2B in tumor-derived EVs for systemic transport to distant organs." (PMID 41463352, 2025). "While the knock-down of S100A10 resulted in increased size of the nodules, S100A11 downregulation reduced tumor growth, consistent with the LPTENKO model, underscoring a MASLD-independent effect." (PMID 40841353, 2025). "Recent studies have demonstrated that S100A10 interacts with annexin A2 (ANXA2) to activate the mTOR pathway, thereby promoting tumor glycolysis and driving malignant tumor progression." (PMID 41195005, 2025). "By doing so, we are mimicking the increased levels of S100A10 observed in human HCC, before tumor formation." (PMID 40841353, 2025). "Differentially gene expression analysis revealed 39 up‐regulated genes in tumours, including VEGFA, NFKBIA, S100A10 and C15orf48." (PMID 41275425, 2025). "Differential expression analysis of TCGA-LIHC tumor tissues and adjacent normal tissues revealed that the expression differences of TMEM45A, S100A10, SERPINA12, BHMT, CFHR3, RPL8, and STMN1 all exceed a 2-fold change." (PMID 39176099, 2024). "The results from flow cytometry revealed that compared to the S100A10-sh-NC group, in the S100A10-sh group, the proliferative capacity (Ki67) and cell vitality (CD69) of CD8+ T cells in the tumor tissue increased." (PMID 39117605, 2024). "Meanwhile, the flow cytometry results showed that compared to the S100A10-sh-NC group, the proliferation capacity (Ki67) and cell viability (CD69) of CD8+ T cells in tumor tissue were enhanced in the S100A10-sh group." (PMID 39117605, 2024).
tumor (continued). "Upregulation of CPT1A and downregulation of SIRT5 synergistically promotes S100A10-K47succ and fibrillin 1 (FBN1) K672succ, resulting in the accumulation of S100A10 and FBN1 in GC cells and further promoting tumor progression." (PMID 38882606, 2024). "In order to further investigate the expression of S100A10 in HCC, we analyzed the expression of S100A10 in different HCC stages by using TCGA database, although the expression of S100A10 in HCC tumor tissues was higher than that in normal tissues." (PMID 37420211, 2023). "In the tumor array, correlations were observed between S100A8 and S100A4 (R = 0.66), S100A9 (R = 0.62) and S100A10 (R = 0.46)." (PMID 37627239, 2023). "In the tumor array, correlations were observed between S100A9 and S100A8 (R = 0.62), S100A4 (R = 0.78), S100A10 (R = 0.51), S100A12 (R = 0.76), and HMGB1 (R = 0.80)." (PMID 37627239, 2023). "SMS can influence the metabolic process and is involved in tumor growth.Overexpression of ACACA, ME1, ADSL or S100A10 promotes HCC growth, migration or invasion, and is connected with poor prognosis." (PMID 36632140, 2023). "Using bioinformatics, we screened six genes for their potential to influence tumor lipid metabolism (ADH1C, APEX1, ME1, S100A10, ACACA, and CYP2C9), and a prognosis model for HCC patients was constructed." (PMID 36456877, 2022). "HUVEC invasion and angiogenesis in the matrigel plug assay were activated by S100A10, while AXL inhibition reduced tumor progression and vessel density in ccRCC tumor xenografts and PDX models." (PMID 34209679, 2021). "They further generated a mathematical algorithm with S100A10 and other markers such as S100A2, TNM stage, to develop a robust model to predict the group of patients with higher prospects of tumor recurrence and poor survival probability." (PMID 34944416, 2021). "Compared with para-cancer tissues, the expression levels of S100A4/S100A6/S100A10/S100A11/S100A13/S100A14/S100P were higher in HCC tissues, while the expression levels of S100A8/S100A9/S100A12 were decreased in tumor tissues." (PMID 33815482, 2021). "Metastatic fibroblasts also express two S100 family proteins, S100A10 and S100A6, which are important in creating inflammation for tumor growth and metastases." (PMID 30383866, 2018). "Here, we demonstrate that the protease‐activating function of S100A10 regulates PDAC cell invasion in vitro and tumor growth in vivo." (PMID 30009399, 2018). "Our data show that several S100 genes, i.e. S100A4, S100A6, S100A10, S100A8, and S100A9, are expressed at very high levels in both tumor cells and TAMs." (PMID 27215396, 2016). "We also detected DLC1 interactions with p120RasGAP, α-catenin, and S100A10 proteins in human cells, and assessed their influence on DLC1’s tumor suppressor function." (PMID 22580498, 2012). "Tumor number incidence and size was monitored in LPTENKO mice with hepatocyte-specific knock-down of S100A10 or S100A11 through in vivo MRI imaging every month, in order to investigate the effect of S100A10/S100A11 downregulation on hepatic carcinogenesis in a MASLD context." (PMID 40841353, 2025). "In tumour cells overexpressing S100A10, Src-mediated phosphorylation of ANXA2 is increased, which may be related to S100A10 promoting the translocation of ANXA2 to the plasma membrane." (PMID 40234383, 2025). "Plg‐RKT reduction in tumor cells, but not reduced S100A10, suppressed metastatic potential in a manner that mimicked plasminogen deficiency." (PMID 37971174, 2024). "No matter HepG2 or SNU449, the growth rate of the tumor was positively correlated with the expression level of S100A10." (PMID 37420211, 2023). "Our previous studies using ectopic subcutaneous tumor models have suggested that plasmin generation and tumor cell infiltration by macrophages are substantially impaired in mice lacking S100A10, which substantially impedes tumor growth." (PMID 37892132, 2023).
tumor (continued). "Higher S100A10 expression was evident in CESC patient tumors relative to healthy tissues (P < 0.001), and correlations were detected between the expression of this gene and clinical parameters including histological tumor type (P < 0.001)." (PMID 37781076, 2023). "S100A10-null TAMs were not able to stimulate angiogenesis and induce tumor growth compared to wild-type macrophages." (PMID 34209679, 2021). "S100A10 participates in the regulation of a variety of tumor and non-tumor diseases through cascade reactions with multitudinous signaling molecules." (PMID 31949486, 2020). "Importantly, expression of the invasion and angiogenesis genes, S100A10, SERPINE1, and VEGFA, increased with tumor grade, and this was also observed for HIF-1α." (PMID 32867190, 2020). "Cell-surface AnxA2 in complex with S100A10, finally, is a key factor in both malignant and non-malignant angiogenesis, and it contributes to tumor cell invasion and metastasis within an inflammatory microenvironment." (PMID 32575495, 2020). "The transcription of S100A10 and SERPINE1 both associated with tumor invasion, was up-regulated in GB patients compared to non-neoplastic control samples." (PMID 32867190, 2020). "This indicates that S100A10 depletion in these cells is sufficient to reduce tumor growth in the absence of tumor‐promoting immune cells." (PMID 30009399, 2018). "Consistent with this, we demonstrate that supplementation with NC derived stromal cells promotes proliferation and tumor aggressiveness in vivo, increasing expression of mesenchymal genes such as CD44, S100A10, ENG, VIM and ACTA2 (SMA), being the last one a typical marker of CAFs." (PMID 29163787, 2017). "Interestingly, expression levels of ACTA2, S100A10 and VIM were positively and significantly correlated to tumor size, suggesting a relationship between NC derived stromal component and tumor growth." (PMID 29163787, 2017). "The tumorigenesis of SPN may be closely related to oxygen metabolism, MYC targets, and DNA repair;SPN tumor cells may originate from pancreatic endocrine progenitor cells;NOV, DCN were nominated as primary and S100A10, MGP as recurrent SPN marker genes, respectively." (PMID 40312910, 2025). "In this study, we compared the expression of S100A10 between PDAC tumor tissues and pancreas non-tumor tissues and further analyzed the correlation between S100A10 expression and clinicopathological characteristics to evaluate its prognostic value for PDAC patients." (PMID 36612197, 2022). "Moreover, S100A10 may form with ANXA2, a heterotetramer, acting as a plasminogen receptor and correlated with tumor aggressiveness and progression." (PMID 36553127, 2022). "Furthermore, we also concluded that down-regulated of S100A6 (F = 3.52, P=0.0164), S100A10 (F = 5.36, P=0.0015), S100A16 (F = 6.69, P=0.00027), and SDC1 (F = 4.02, P=0.00849) were effectively related to lower tumor stage." (PMID 35342420, 2022). "S100A10 plays an important role in a variety of tumor and non-tumor diseases." (PMID 31949486, 2020). "S100A4, cathepsin B, cyclin B1, Annexin A2, S100A10, TRIM21, 14-3-3 ζ/δ, and Ezrin may hence participate in tumor invasion depending on the grade of human CRCs, and protein upregulation during lymph node metastasis also suggests a positive correlation with metastasis in human CRCs." (PMID 32154176, 2020). "Moreover, in vascular co-option areas, the blood vessels, showing a reduced CD31 expression compared to sprouted vessels, appear surrounded by P-gp- or S100A10-positive tumor cells with a not-indifferent expression of mitochondria, indicative of boosted metabolic activity in tumor cells." (PMID 36553127, 2022). "However, targeting S100A11 downregulation to attenuate liver tumor incidence, although potentially promising approach, it also leads to the downregulation of the hepatoprotective S100A10, which might explain the absence of beneficial outcome on tumor incidence." (PMID 40841353, 2025).